FBXL15 (F-box and leucine rich repeat protein 15)
Description:
Substrate recognition component of a SCF (SKP1-CUL1-F-box protein) E3 ubiquitin-protein ligase complex which mediates the ubiquitination and subsequent proteasomal degradation of SMURF1, thereby acting as a positive regulator of the BMP signaling pathway. Required for dorsal/ventral pattern formation and bone mass maintenance. Also mediates ubiquitination of SMURF2 and WWP2.
Synonyms: FBXO37; MGC11279; Fbl15; JET
Tractability: PROTAC: ubiquitination databases record sites on it; its protein half-life has been measured.
Gene: Protein-coding gene on chromosome 10 (102,418,520 to 102,423,142, forward strand). Ensembl gene ENSG00000107872.
Subcellular location: Cytoplasm
Pathways (Reactome):
Immune System: Antigen processing: Ubiquitination & Proteasome degradation
Metabolism of proteins: Neddylation
Gene Ontology:
Molecular function: protein binding
Biological process: G2/M transition of mitotic cell cycle; positive regulation of BMP signaling pathway; protein ubiquitination; SCF-dependent proteasomal ubiquitin-dependent protein catabolic process; bone mineralization; dorsal/ventral pattern formation; regulation of BMP signaling pathway
Cellular component: cytoplasm; SCF ubiquitin ligase complex; cytosol
Genetic constraint (gnomAD): Loss-of-function variants: 19 observed, 15.85 expected, observed/expected ratio (o/e) 1.2, 90% interval 0.83 to 1.73. The synonymous counts are far from expectation, so gnomAD's model fits this gene poorly and the ratio says little. Missense variants: 385 observed, 335.22 expected, observed/expected ratio (o/e) 1.15, 90% interval 1.06 to 1.25. Synonymous variants: 224 observed, 160.38 expected, observed/expected ratio (o/e) 1.4, 90% interval 1.25 to 1.56.
Homologues: Orthologues: chimpanzee FBXL15 (99% identical), macaque FBXL15 (98% identical), pig FBXL15 (97% identical), mouse Fbxl15 (96% identical), rabbit FBXL15 (96% identical), dog FBXL15 (93% identical), guinea pig FBXL15 (92% identical), rat Fbxl15 (90% identical), zebrafish fbxl15 (58% identical), tropical clawed frog fbxl15 (54% identical), Drosophila melanogaster CG8272 (22% identical), Drosophila melanogaster CG5003 (22% identical), and 24 more. Paralogues in human: FBXL18 (22% identical), FBXL4 (21% identical), FBXL7 (21% identical), FBXL19 (20% identical), FBXL20 (20% identical), FBXL13 (20% identical), FBXL2 (20% identical), FBXL6 (18% identical), FBXL16 (18% identical), SKP2 (18% identical), FBXL14 (17% identical), FBXL5 (17% identical), and 3 more.
Diseases named in the same sentence as FBXL15 in open-access papers:
FBXL15 is named in the same sentence as 1 disease in open-access papers, as found by Europe PMC text mining. Sharing a sentence is not in itself a finding about the gene and the disease.
FBXL15 shares sentences with these, for which no sentence is quoted: renal cell carcinoma (1 paper).